AKT1 (AKT serine/threonine kinase 1)
Diseases named in the same sentence as AKT1 in open-access papers (continued):
Sharing a sentence is not in itself a finding about the gene and the disease.
breast cancer (continued). "This study evaluates radio-iodinated anastrozole ([125I]anastrozole) and epirubicin ([125I]epirubicin) for AKT1-targeted breast cancer therapy, utilizing radiopharmaceutical therapy (RPT) for personalized treatment." (PMID 39275052, 2024). "The international data sharing consortium, AACR Project GENIE, showed that genetic alterations in PIK3CA, PTEN and AKT1 occur in ~36%, 7% and 5% of breast cancer, respectively." (PMID 39251829, 2024). "The identification of specific genetic alterations within the AKT1 gene, particularly within the pleckstrin homology domain (PH), has been substantiated in breast cancer cases." (PMID 38172946, 2024). "This study represents the first comprehensive in silico exploration of the binding potential of radioiodinated anastrozole ([125I]anastrozole) and epirubicin ([125I]epirubicin) against the AKT1 enzyme, a critical target in breast cancer therapy." (PMID 39275052, 2024). "In summary, our study confirms that hyperactivated AKT1 in endocrine‐resistant breast cancer can interact with TBK1 to block the activation of cGAS‐STING signaling." (PMID 39023171, 2024). "In contrast, AKT1 downregulated was enough to predict inhibited breast carcinoma metastasis, correlating with the least aggressive behavior of breast cancer’s HER2− molecular subtype in the Latino population." (PMID 38337803, 2024). "Here, we demonstrated that ropivacaine significantly suppressed the stemness and chemoresistance in breast cancer cells by serving as the AKT1 specific inhibitor and subsequent repressing the expression of GGT1." (PMID 38523299, 2024). "Depletion of GGT1 diminished stem phenotypes of breast cancer cells, indicating the formation of NF-κB /AKT1/GGT1/NF-κB positive feedback loop in the regulation of ropivacaine-repressed stemness in breast cancer cells." (PMID 38523299, 2024). "Here, we uncover that positive feedback loop of inactivated cGAS‐STING pathway and hyperactivated AKT1 is a crucial determinant of endocrine resistance in breast cancer." (PMID 39023171, 2024). "A study of Chinese breast cancer patients showed a significant correlation between AKT1 methylation levels and HER2 status (p = 0.0249), with low methylation and suppressed expression of AKT1 being associated with HER2-negative tumors." (PMID 39769140, 2024). "In transgenic mouse models of mammary carcinoma, driven by Erbb2 and polyomavirus middle T-ag (PyMT), germline Akt1 gene ablation inhibited primary tumor development and, although increased tumor invasiveness, it did not increase the risk of metastasis." (PMID 39614261, 2024). "We conclude, that AKT1-inhibition in combination with radiotherapy contribute to novel treatment strategies for breast cancer brain metastases." (PMID 37483521, 2023). "A statistically significant difference in the AKT-1 (rs1130233 G > A genotypes was seen between breast cancer patients and healthy controls (p < 0.0001)." (PMID 36831624, 2023). "From breast cancer actionability, PIK3CA (ESCAT Tier IA) was reported in 39.4% (n = 97), AKT1 mutation (ESCAT Tier IIB) in 45.9% (n = 113), and ERBB2 mutation (ESCAT Tier IIB) in 17.1% (n = 42) of early-stage Taiwanese breast cancers." (PMID 37760445, 2023). "As an example, AKT1 has been shown to suppress breast cancer cell migration and invasion in in vitro studies, while AKT2 promotes these processes, potentially facilitating cancer metastasis." (PMID 37513905, 2023). "in Taiwanese patients with breast cancer identified PIK3CA as one of the most frequently mutated genes in 38% of the study population, followed by ERBB2 (23%), ESR1 (10%), AKT1 (6%), and BRCA2 (5%) mutations." (PMID 37655108, 2023). "The study identified 33 common targets of PPIs at the intersection of breast cancer and diabetes, where AKT1 and MMP9 were found to be the core targets." (PMID 37165049, 2023). "An actin binding protein, paladin, phosphorylated by Akt1 on S507, inhibits breast cancer cell migration by disrupting F-actin bundles." (PMID 38002001, 2023).
breast cancer (continued). "Previous research studies have not extensively elucidated the correlation of genotypes and allele variations of the PI3K, AKT-1, KLF-14, MDM4 and miRNAs 27a, miR-196a genes with the predisposition of Breast cancer in Saudi Arabia." (PMID 36831624, 2023). "The molecular docking investigation revealed that among the nine phytoconstituents, 8-hydroxycoumarin showed the best binding energy (−9.2 kcal/mol) with the Akt1 breast cancer target." (PMID 37724182, 2023). "A significant correlation was reported in the recessive inheritance model between AKT-1(GG + GA) and AKT1-AA genotypes and breast cancer susceptibility with an OR = 5.5, (95%) CI = 1.185–26.036, RR = 3.15, and p < 0.029." (PMID 36831624, 2023). "For example, the overexpression of miR-215 leads to the suppressed growth and penetration of breast cancer cells by targeting AKT1." (PMID 35647303, 2022). "AKT1 is a therapeutic target for AKT1 inhibitors, which have been shown to be effective in inhibiting breast cancer cell lines." (PMID 35740845, 2022). "INPP5J regulates AKT1-dependent breast cancer growth and metastasis and predicts recurrence in lung adenocarcinoma." (PMID 35615380, 2022). "Representative experimental validation studies in two breast cancer cell lines showed a reasonable concurrence between the expression data from the RNA-sequencing and qRT-PCR or data from ex vivo inhibition of AKT1 activity in cancer patient-derived cells." (PMID 35892586, 2022). "Downregulation of AKT1 in mechanistic experiments dephosphorylate PIKfyve on Ser and inactivate the PIKfyve site, resulting in mammary cancer metastasis through EGFR signaling pathways." (PMID 35341150, 2022). "Studies have shown that knockdown of AKT1 stimulates the nuclear translocation of β-catenin, leading to breast cancer cell infiltration." (PMID 35341150, 2022). "Akt1 has been demonstrated to regulate miR-200a-5p in TGFβ-induced EMT in human breast cancer cells." (PMID 35406397, 2022). "The mutation list is highly similar to the finding in breast cancer of unspecified genotypes (PIK3CA H1047R E545K N345K, and AKT1 E17K)." (PMID 36298462, 2022). "We report that this specific AKT1 mutant is able to initiate mammary tumors in female mice at high efficiency." (PMID 35681625, 2022). "In general, AKT1 knockdown leads to inhibition of tumor growth via blocking the cell-cycle progression and/or promoting apoptosis in breast cancer model systems." (PMID 35892586, 2022). "A heavily pre-treated AKT1 D323G-mutant breast cancer patient with ER-positive HER2-negative mixed ductal and lobular carcinoma had stabilization of her disease lasting 16 weeks before progressing." (PMID 35440569, 2022). "In this context, here we uncovered the effect of the status of AKT1 as well as inhibition of AKT’s kinase activity on the genome-wide transcriptomic and differential splicing events in breast cancer cells." (PMID 35892586, 2022). "In brief, findings presented here provide a resource for further understanding of AKT1-dependent modulation of gene expression in breast cancer cells and broaden the scope and significance of AKT1 targets and their functions." (PMID 35892586, 2022). "Among them, the activation of AKT1 can inhibit apoptosis in breast cancer cells and increase its survival rate." (PMID 35311116, 2022). "In breast cancer, AKT activation is apparently an early event, since phosphorylated AKT is observed in ductal carcinoma in situ and AKT1 mutations are detected at a high frequency in benign papilloma." (PMID 35681625, 2022).
breast cancer (continued). "In brief, results presented here shed new insights on the significance of AKT1 signaling on the genome-wide transcriptome and differential splicing in breast cancer cells." (PMID 35892586, 2022). "Upregulation of AKT1 and cancer promotion have been reported by several researchers into liver gastric, colorectal, and breast cancers." (PMID 35611247, 2022). "AKT1 promotes cell proliferation and reduces the migration of breast cancer cells, while AKT2 promotes migration and invasion of cancer cells." (PMID 35456460, 2022). "PIK3CA/AKT1/PTEN alterations are frequently observed in breast cancer, including approximately 50% of patients with hormone receptor-positive (HR+) breast cancers, and contribute towards a negative prognosis and resistance to endocrine therapies." (PMID 34860318, 2022). "The Akt family includes three members (Akt1, Akt2 and Akt3) that play distinct roles in breast cancer malignancy, being Akt1 correlated with proliferation of tumor cells and the other two isozymes variously involved in invasion/metastasis." (PMID 35743776, 2022). "A similar observation was also obtained from a recent article regarding breast cancer research showing that increased Akt1 SUMOylation skewed macrophages toward M2 polarization within the breast cancer microenvironment, eventually promoting tumor progression." (PMID 36428622, 2022). "The gain-of-function mutation in the pleckstrin homology domain of AKT1 (AKT1E17K) occurs in lung and breast cancer." (PMID 35681625, 2022). "In particular, homologs AKT1, AKT2, ERBB2, FGFR2, and PIK3CA in CGC play important roles in breast cancer progression, mediating breast cancer risk, corresponding to the driver candidates RPS6KA1, SGK1, PTK2, IGF1R, PIK3CB, and PRKDC predicted by DriverMP." (PMID 38091511, 2022). "H1047R (PIK3CA), E545K (PIK3CA), E17K (AKT1), and N345K (PIK3CA) produced recurrent neoantigens and had a higher mutation frequency in the breast cancer cohort." (PMID 35387130, 2022). "In summary, our study showed that SENP3 plays an important role in fine‐tuning macrophage polarization towards M2 in breast cancer via de‐SUMOylating Akt1." (PMID 33932085, 2022). "Here, we delineate the impact of selective AKT1 knock down using gene-specific siRNAs or inhibiting the AKT activity with a pan-AKT inhibitor VIII on the nature of transcriptomic changes in breast cancer cells using the genome-wide RNA-sequencing analysis." (PMID 35892586, 2022). "Our work represents the first mouse model that developed mammary tumors dependent on the constitutively activation of AKT1 by E17K substitution." (PMID 35681625, 2022). "Our experimental strategy involved selectively knocking down the endogenous AKT1 as well as treating the model breast cancer cells with a pan-AKT activity Inhibitor VIII." (PMID 35892586, 2022). "Akt1 can also inhibit breast cancer cell migration and invasion by phosphorylating paladin at S507, an actin binding protein involved in actin cytoskeleton organization and cell migration." (PMID 36180910, 2022). "Several genetically modified mouse strains have been generated to model the role of the PI3K/AKT pathway in breast cancer, including mammary-specific knockout of PTEN, mammary-specific expression of mutant PIK3CA, or myristoylated AKT1." (PMID 35681625, 2022). "Our previous work indicated that HSF1 can be activated by AKT1 via phosphorylation at S326 in breast cancer cells." (PMID 35080342, 2022). "For instance, depletion of INPP5J reduces cell migration and invasion by regulating AKT1 signaling in breast cancer." (PMID 34996491, 2022). "In BJ-TERT and human mammary epithelial cells (HMEC), overexpressing AKT1E17K, a clinically relevant activated mutant form of AKT1 in multiple cancer types including breast cancer and ovarian cancer, also enhanced CBS protein expression." (PMID 35758651, 2022). "After prognosis analysis, we found four genes (AKT1, ERBB2, KMT2C, and USP34) associated with survival of breast cancer." (PMID 34408553, 2021).
breast cancer (continued). "The regulatory network TRIM24 was involved in showed that TRIM24, YAP1, Ifn, Ifnar, SOCS1, and S100A8 together activated atherogenesis and cell viability of breast cancer cell lines through 18 genes, including AKT1, ID2, etc.." (PMID 34575874, 2021). "It was then realized that Akt1 and Akt2 have opposite roles in breast cancer initiation and progression." (PMID 34298660, 2021). "The analysis of the data contained in TCGA confirmed the lower level of PIK3CA, PIK3R1 and PTEN gene expression in breast cancer tissues compared to normal tissues and a higher level of AKT1 gene." (PMID 33669698, 2021). "Other genes in the PI3K pathway, such as PTEN, AKT1 and PIK3R1, are also mutated in breast cancer but with much lower frequency." (PMID 33664847, 2021). "Akt1 was highly expressed in ER-positive recurrent breast cancers and negatively affected overall survival of breast cancer patients." (PMID 34298660, 2021). "The analysis of the data contained in TCGA confirmed a lower level of PIK3CA, PIK3R1 and PTEN gene expression in breast cancer tissues compared to normal tissues and a higher level of the AKT1 gene." (PMID 33669698, 2021). "Based on TCGA dataset, Akt3 is most amplified followed by Akt2 and amplification of Akt1 was least among Akt isoforms in breast cancer." (PMID 34298660, 2021). "It has been reported that the over-expression of Akt1 by the activation of HER2/PI-3K confers a broad-spectrum chemoresistance on breast cancer cells." (PMID 34439105, 2021). "Akt1 gene expression signature positively correlated with cyclin D1 gene expression signature in different subtypes of breast cancer with highest significance in luminal A, luminal B and basal type." (PMID 34298660, 2021). "The chemokine receptor CXCR2 promoted breast cancer cell migration, invasion, and metastasis by suppressing Akt1." (PMID 34298660, 2021). "A balance between Akt1 and Akt2 decided the invasiveness and metastasis of primary and metastatic breast cancers by differential regulation of miR-200." (PMID 34298660, 2021). "Overexpression of Akt1 in MDA-MB-231 cells was shown to counteract the effects of the chemokine receptor CXCR2 on breast cancer cell growth, metastasis and chemoresistance by inducing senescence." (PMID 34298660, 2021). "Constitutive activation of Akt1 inhibited doxorubicin-induced senescence but appears to augment tamoxifen-induced senescence in breast cancer MCF-7 cells." (PMID 34298660, 2021). "Similar to the blocking of breast cancer metastasis by halting Akt-activated cell proliferation by Rg3 and Rd, CK ginsenoside repressed Akt1 signaling to promote apoptosis in SKBR3 cells." (PMID 33623532, 2021). "Phase III IPATunity130 is currently evaluating ipatasertib and paclitaxel for PIK3CA/AKT1/PTEN-altered advanced HER-2- breast cancer (NCT03337724)." (PMID 33435254, 2021). "The PI3K pathway is hyper-activated in >60% of clinical breast cancers due to aberrations in genes encoding HER2, PTEN, PIK3CA, or AKT1-3." (PMID 33669867, 2021). "The highest expression of AKT1 was found in breast cancer cell lines, with a median of 5.8 among 60 cell lines, but the heterogeneity was also the largest." (PMID 33967754, 2021). "Consistently, pretreatment of bone-metastatic breast cancer cells with an AKT1/2-inhibitor leads to a diminished bone metastasis." (PMID 34064589, 2021). "AKT serine/threonine kinase 1 can be target by microRNA-215 to regulate the progression of breast cancer." (PMID 34539736, 2021). "For instance, miR‐520c‐3p inhibits the invasion and migration of breast cancer by targeting IL‐8 and suppresses the invasion and migration of lung cancer by targeting AKT1 and AKT2." (PMID 33340250, 2021). "The next pathway, ESR1, which was mutated in breast cancer, received microenvironment factor S100A4 to regulate TF ETS1 and SMAD3 through signaling transduction proteins ZNF516, PIK3R1, IDH1, and AKT1." (PMID 33802957, 2021).
breast cancer (continued). "miR-409-3p reduced proliferation, decreased invasion and migration of breast cancer cells in vitro by downregulating AKT1." (PMID 33498407, 2021). "In another study, AKT1 was observed to be central to the reduction of breast cancer invasiveness by another tumor suppressor called TIS21." (PMID 33498407, 2021). "AKT has three isoforms, AKT1, AKT2 and AKT3, with highly conserved domain structure, which are associated with breast cancer progression and play different roles in breast cancers." (PMID 34503444, 2021). "The somatic mutations and amplification in pleckstrin homology (PH) domain (E17K) of Akt1 have been identified in various cancers, such as pancreatic, colorectal, and ovarian, and breast cancers." (PMID 34830339, 2021). "exon 9–10) PIK3R1, PTEN, AKT1, mTOR, was obtained using the real-time PCR technique in 54 breast cancer patients." (PMID 33669698, 2021). "Phosphorylation of palladin by Akt1 promotes F-actin bundling and inhibits breast cancer cell migration." (PMID 34419139, 2021). "Various genomic alterations and genomic signatures, including ERBB2 amplification, mutations in PIK3CA, AKT1, and ESR1, and tumor mutational burden (TMB), have become important biomarkers for treatment selection in breast cancer (BC)." (PMID 33968723, 2021). "AKT1 expression is higher than AKT2 during the later stages of tumour development in oncogene-driven murine mammary cancer models." (PMID 33276499, 2020). "ARHGAP29 and AKT-1 expression was examined in a control group and in breast cancer cells transiently transfected with ARHGAP29-specific siRNA." (PMID 33291460, 2020). "As in luminal breast cancer, this activation involves PIK3CA and AKT1 mutations to a greater extent than PTEN loss (which is more frequently reported in TNBC in general)." (PMID 32042320, 2020). "It is important to note that in this study on Chinese breast cancer patients the frequency of PIK3R1, AKT1, AKT2, AKT3, and PDK1 mutations was higher than that observed in the TCGA data set." (PMID 32210163, 2020). "Inspired by these considerations, AKT1 was investigated as a further target in addition to ARHGAP29 for expression analyses to compare breast cancer cells with reduced and normal ARHGAP29 expression and to investigate a possible signal cascade around ARHGAP29." (PMID 33291460, 2020). "Important, this was observed in tumor cell lines and biopsies from AKT-high sporadic breast cancers, thereby illustrating that AKT1 inhibits homologous recombination in breast cancer cells in vitro and in vivo." (PMID 33266502, 2020). "For example, a study on human breast cancer cell lines showed that AKT1 inhibits cell migration and invasion, while using mouse embryonic fibroblasts AKT1 has been found to promote migration." (PMID 32664456, 2020). "Targeting the PI3K pathway upstream at AKT has had limited efficacy in breast cancers as shown with the selective AKT1/2 inhibitor, ipatasertib." (PMID 32795346, 2020). "AKT1 exerts an inhibitory effect on breast cancer cell migration by destabilising TSC2, resulting in decreased activation of Rho and also by promoting the degradation of the transcription factor NFAT1 in a GSK3β-dependent manner." (PMID 33276499, 2020). "Network analysis further reveals that Prunella vulgaris L. produces therapeutic effects on breast cancer by inhibiting key targets in the ErbB signaling pathway and estrogen signaling pathways, such as AKT1, EGFR, and MYC." (PMID 32978480, 2020). "A single amino acid substitution E17K of AKT1 was described in several cancers, with the highest incidence 3.8%, in breast cancer." (PMID 32605126, 2020).